WNT5A (Wnt family member 5A)
Diseases named in the same sentence as WNT5A in open-access papers (continued):
Sharing a sentence is not in itself a finding about the gene and the disease.
gastric cancer (continued). "Regarding the role of Wnt5a specifically in GC, it must be noted that overexpression of Wnt5a during adulthood failed to induce tumor initiation, thus suggesting that Wnt5a alone is not sufficient for gastric cancer establishment." (PMID 32195251, 2020). "Although Wnt5a transcription can by modulated by multiple mechanisms, such as Hedgehog and TGF-β signaling cascades, it remains unclear whether and if so, how EGF can regulate Wnt5a in gastric cancer cells." (PMID 25779663, 2015). "This study reveals that Wnt5a is overexpressed in gastric cancer tissues in mRNA level, which is consistent with another study showing Wnt5a overexpression in protein level by immunohistochemistry, however, Wnt5a overexpression has not been found in some gastric cancer cell lines." (PMID 24993819, 2014). "In addition, blocking WNT5A-mediated ROR2 internalization suppressed gastric cancer tumor cell invasion and metastasis in WNT5A-high but not WNT5A-low cells, suggesting a direct role for ROR2 in activating the Wnt/PCP pathway rather than a chemokine signaling pathway." (PMID 37722040, 2023). "Notably, reduced RNF43 function is a negative prognosis factor in gastric cancer patients and RNF43 loss-of-function type of mutation exacerbated Helicobacter pylori-induced gastric tumor carcinogenesis associated with the upregulation of WNT5A mRNA level." (PMID 34702444, 2021). "Also, other gene/protein expression differences have recently been identified, including the presence of WNT5A expression in gastric cancers (not expressed in cell lines) and differences in DNA methylation and gene expression signatures between colorectal carcinomas and colon cancer cell lines." (PMID 22194833, 2011). "WNT5A activates the nonclassical Wnt/Ca2+ pathway by binding to the FZD2 and promotes the invasion and migration of gastric cancer cells." (PMID 38952556, 2024). "WNT1 is involved in the maintenance and proliferation of GCSCs through the classical Wnt pathway, and WNT5A is involved in the initiation of the EMT and gastric cancer stem cell proliferation through the nonclassical Wnt pathway." (PMID 38952556, 2024). "Although the current study has contributed to the mechanistic understanding the role of Wnt5a in EGF-induced gastric cancer cell EMT, the issue as to how Wnt5a precisely regulates EMT in gastric cancer cells is unlikely to be settled in this paper." (PMID 25779663, 2015). "Moreover, this study has shown that rIL-1Ra can suppress Wnt5a-induced MCP-1 upregulation and macrophage chemotaxis, suggesting IL-1β blocking may be used to inhibit the aberrant macrophage infiltration, and suppress the development of chronic gastric inflammation and gastric cancer." (PMID 24993819, 2014). "RHOA, a downstream component of non-canonical Wnt signalling and FZD7, is upregulated in GC, whilst ROR1, a tyrosine kinase like receptor able to transmit non-canonical Wnt5a signals, is phosphorylated in HS746T human gastric cancer cells, via a Met dependant mechanism." (PMID 27196929, 2016). "Wnt5a stimulated both invasion and proliferation of certain types of cancer cells, including HeLaS3 cervical cancer cells and A549 lung cancer cells although Wnt5a promoted invasion but not proliferation in other cancer cells such as KKLS gastric cancer cells." (PMID 25622531, 2015).
prostate carcinoma (90 papers, 2009 to 2025). A carcinoma that arises from epithelial cells of the prostate gland. "Preclinical studies have demonstrated that low levels of WNT5A are associated with a more advanced or metastatic progression in breast and prostate cancers." (PMID 39123414, 2024). "Immunohistochemical evaluations of primary tumor tissues from breast, colon, hepatocellular and prostate cancer patients illustrate that loss of or reduction in WNT5A protein expression correlates with shorter recurrence-free survival and thus poor prognosis." (PMID 37998393, 2023). "The upregulated expression of the epithelial to mesenchymal transition genes CAMK2N1 and WNT5A is associated with the progression of prostate cancer." (PMID 38025757, 2023). "Murine Ctnnb1-mutant prostate cancer spheroids are also reported to be enzalutamide resistant but responsive to Wnt5a loss." (PMID 35204808, 2022). "Wnt5a is generally found to be upregulated in prostate cancer, but results are inconsistent regarding its association with good or poor prognosis." (PMID 28030815, 2017). "It has previously been shown that preserved expression of WNT5A in the primary tumor is associated with increased time to biochemical recurrence in patients with low-grade prostate cancer." (PMID 28886116, 2017). "Genes encoding secreted proteins ADAMTS1, IGFBP5 and WNT5A were significantly down-regulated in NCCIT cells co-cultured with CD90+ prostate cancer-associated fibroblasts compared to induction by normal prostate stromal cells." (PMID 24260246, 2013). "Our group has recently shown that preserved high protein expression of Wnt5a in prostate cancer is associated with longer relapse-free time after radical prostatectomy." (PMID 23342259, 2012). "High levels of Wnt5a expression have been associated with osteosarcoma, prostate carcinoma and metastatic melanoma." (PMID 22574198, 2012). "WNT5A has recently been implicated in the progression of prostate cancer, however, the receptors that mediate its effects remain unknown." (PMID 29930766, 2018). "Additionally, we also investigated the possibility that WNT5A signaling caused a reduced secretion of MMP9 in prostate cancer cells." (PMID 28886116, 2017). "In a prostate cancer model using transgenic mice, the onset of prostatic tumorigenesis as well as tumor growth was significantly potentiated by introduction of an AR point mutation (AR T877A) into the prostate and genetic screening of mice identified Wnt-5a as an activator." (PMID 22325146, 2012). "Studies conducted by a team led by Xie have shown that the function of the Wnt5a protein in prostate cancer depends on the stage of the disease and the tissue context." (PMID 41465498, 2025). "Bone metastasis of prostate cancer acquired resistance to androgen deprivation through WNT5A‐mediated BMP‐6 induction." (PMID 39789383, 2025). "QRT-PCR analysis revealed lower expression of the β-catenin, Fzd8, Wnt5a and cyclin D1 genes in prostate cancer compared to benign prostatic hyperplasia tissues." (PMID 41465498, 2025). "Foxy-5, a peptide mimic of WNT5A, increases the expression level of WNT5A and prevents tumor metastasis in the breast and prostate cancer contexts." (PMID 38952556, 2024). "Studies in transgenic mouse models show that Wnt-5a can act as an activator of AR-mediated prostate cancer growth and Wnt-5a-mediated activation of β-catenin signaling can cooperate with Pten loss to drive AR-independent CRPC." (PMID 38531859, 2024). "In prostate cancer cell lines, Wnt5a expression was upregulated due to epigenetic influences that rendered the cancer cells highly invasive." (PMID 39123414, 2024). "We previously touched on how the expression of Wnt5a, an activator of quiescence for breast and prostate cancer cells, declines with age and possibly contributes to relapse in older age." (PMID 37608096, 2023).
prostate carcinoma (continued). "Foxy-5 is a WNT5A-mimicking peptide that specifically impairs prostate cancer invasion by inhibiting endothelial tumor cell migration through activation of Wnt-5a-mediated signaling." (PMID 36900412, 2023). "In vivo studies using mouse models of prostate cancer confirmed that addition of Wnt5a reduces tumour burden (prolonged dormancy), while Wnt5a knockdown leads to increased detectable metastatic foci in the bone, which appeared sooner than in wild-type mice." (PMID 37608096, 2023). "WNT5A is upregulated in prostate cancer and can promote tumor cell invasion through FZD2 and ROR246." (PMID 37524814, 2023). "One example is secreted Wnt5a, which has been shown to induce quiescence in the prostate cancer cell line, PC-3, in vitro." (PMID 37608096, 2023). "Wnt5a is a promoter of prostate cancer dormancy in the BM through a mechanism by which it represses canonical Wnt signaling that promotes tumor progression." (PMID 37296983, 2023). "Accordingly, recombinant WNT5A significantly reduces the migration and invasion of breast, colon, hepatocellular and prostate cancer cells." (PMID 37998393, 2023). "Wnt5a from the osteoblastic niche has also been shown to induce prostate cancer cell dormancy in bone in the intra-tibial PC-3 xenograft model, involving the inhibition of Wnt/β-catenin signaling through the potentiation of ROR2-SIAH2 signaling." (PMID 35204808, 2022). "For example, bone marrow stromal cells can produce Wnt5A to attract prostate cancer cells to migrate into the bone." (PMID 35927755, 2022). "FZD5 has been identified to be a preferred receptor of Wnt5a, which mediates the antiproliferative and proapoptotic effects in prostate cancer, and inflammatory reactions in sepsis." (PMID 34564708, 2021). "Prostate cancer cells (PC-3) stimulated by Wnt ligands (Wnt5A, Wnt10B) were analyzed by Cy3-PLA for the co-localization of FZD6 and co-receptors (canonical: LRP6, non-canonical: ROR1) at the single-cell level." (PMID 34769487, 2021). "In a single cell RNA sequencing study of prostate cancer patient CTCs, Miyamoto and colleagues identified Wnt5A as a key regulator, especially for antiandrogen resistance." (PMID 34685470, 2021). "For example, treating prostate cancer cells with Wnt5A promotes their dormancy in bone through the Wnt5A/ROR2/SIAH2 axis." (PMID 34685686, 2021). "The Wnt5a signaling pathway is involved in the progression of several cancers; Wnt5a contributes to the progression of gastric, lung, and prostate cancers, but serves as a tumor suppressor in thyroid and ovarian cancers." (PMID 34047951, 2021). "Previous studies suggested that FDZ5 involved in mediating the proapoptotic and antiproliferative effects of WNT5A in prostate cancer." (PMID 33101546, 2020). "miR-1253 regulates the expression of the long, non-coding RNA FOXC2-AS1 in prostate cancer cells and WNT5A in lung carcinoma." (PMID 32443852, 2020). "To determine the cell-cell interaction inferred above, we treated castration-resistant prostate cancer cells 22RV1 with WNT5A and generated RNA-seq data." (PMID 31504033, 2019). "Amongst all FZD receptors, FZD5 was one of the most highly expressed receptors in the prostate cancer cell lines and WNT5A also showed a stronger binding response to FZD5 than to RYK." (PMID 29930766, 2018). "In prostate cancer, WNT5A exerts potent anti-tumor effects by suppressing tumor cell proliferation and inducing apoptosis." (PMID 29930766, 2018). "After demonstrating that WNT5A reduces prostate cancer cell proliferation and induces apoptosis, we sought to investigate which receptors were responsible for these effects." (PMID 29930766, 2018). "miR-377 also controls the proliferation, apoptosis, migration, and invasion in metastatic prostate cancer cells by targeting FZD4 whereas miR-101 suppresses the WNT5a-induced proliferation of lung fibroblasts by targeting FZD4/6." (PMID 30574422, 2018).
prostate carcinoma (continued). "Extensive in vitro analyses revealed that the WNT5A receptors FZD5 and RYK mediate the anti-tumor effects of WNT5A on prostate cancer cells." (PMID 29930766, 2018). "Taken together, the data suggest a more prominent role of WNT5A/FZD5 than WNT5A/RYK signaling in prostate cancer." (PMID 29930766, 2018). "In conclusion, this study suggests that FZD5 and RYK are the predominant receptors for mediating the pro-apoptotic and anti-proliferative effects of WNT5A in prostate cancer in vitro." (PMID 29930766, 2018). "After having previously shown that WNT5A exerts potent anti-tumor effects in prostate cancer cells, this study aimed to investigate which of the receptors mediates its anti-tumor effects." (PMID 29930766, 2018). "Here, we identified Wnt receptors that are highly expressed in prostate cancer and investigated which of these receptors mediate the anti-tumor effects of WNT5A in prostate cancer in vitro." (PMID 29930766, 2018). "WNT5A expression and function have also been related to prostate cancer, but there have been conflicting reports regarding the role of this protein in the progression of this disease." (PMID 28886116, 2017). "Prostate cancer patients with high WNT5A expression in their tumors have been shown to have more favorable prognosis than those with low WNT5A expression." (PMID 28886116, 2017). "One study examining a small cohort of prostate cancer patients indicated a worse outcome for patients with high endogenous WNT5A levels in their cancer tissues." (PMID 28886116, 2017). "To establish an adequate model for studying the role of WNT5A in prostate cancer progression and in particular in metastasis, we first searched for suitable prostate cancer cell lines." (PMID 28886116, 2017). "In conclusion, this study shows that the WNT5A-mimicking peptide Foxy-5 significantly reduces the early metastatic spread of WNT5A-low DU145 prostate cancer cells in an in vivo orthotopic xenograft mouse model." (PMID 28886116, 2017). "These contradictory results include reports of different in vitro responses to recombinant WNT5A (rWNT5A) in prostate cancer cells and different prognostic values for WNT5A expression in human prostate cancer tissue." (PMID 28886116, 2017). "To explore this idea, we have in the present study used Foxy-5, a WNT5A mimicking peptide, to investigate its impact on primary tumor and metastasis in vivo and on prostate cancer cell viability, apoptosis and invasion in vitro." (PMID 28886116, 2017). "In the present study we injected WNT5A-low DU145 or WNT5A-high PC3 prostate cancer cells into the prostate of mice and then let the primary tumors establish for a period of one to three weeks before the treatment with Foxy-5 was initiated." (PMID 28886116, 2017). "This analysis detected increased activation of NCWP through Wnt5a/ Fzd2 as the most common mode of Wnt activation in prostate cancer." (PMID 28030815, 2017). "Knockdown and overexpression of Wnt5a in human prostate cancer cell lines reduced and stimulated the invasion activities of PCa cells, respectively." (PMID 27191743, 2016). "On the other hand, Wnt5a overexpression induced prostate cancer cell apoptosis, reduced proliferation, diminished tumor growth and prevented the establishment of bone lesions in vivo model." (PMID 27571105, 2016). "WNT-5A expressed by bone marrow stromal cells induces expression of BMP-6 in prostate cancer cells via a PKC-NFκB pathway." (PMID 26514730, 2016). "Hypomethylation of the WNT-5A promoter in prostate cancer cells accounts for the increased transcription of WNT-5A in these cells." (PMID 26514730, 2016). "WNT-5A regulates motility in prostate cancer cells as well by promoting actin remodeling via Ca2+-CaMKII signaling." (PMID 26514730, 2016). "Another study showed that Wnt5a was highly expressed in prostate cancer cells that were derived from a bone metastasis site." (PMID 27571105, 2016).
prostate carcinoma (continued). "Wnt5a is upregulated in prostate cancer cells compared to normal prostate cells due to hypo-methylation of the gene promoter region." (PMID 27571105, 2016). "Bone stromal cell derived-Wnt5a induced the expression of BMP-6 through activating the PKC/NFkB pathway in prostate cancer cells." (PMID 27571105, 2016). "WNT5A is found overexpressed in different solid tumors, such as in lung cancer, prostate cancer, metastatic carcinomas, and squamous head and neck carcinomas." (PMID 26316480, 2015). "Knockdown and overexpression of Wnt5a in human prostate cancer cell lines reduced and stimulated respectively, invasion activity." (PMID 23383207, 2013). "Wnt5a expression in prostate cancer tissues has been correlated with high Gleason scores and biochemical prostate cancer relapse." (PMID 23383207, 2013). "We also noted a positive association between Wnt-5a expression and VEGF-A expression, in accordance with previous findings in prostate cancer." (PMID 23990917, 2013). "Knockdown and over-expression of Wnt-5a reduced and stimulated, respectively, the invasion and migration activities of prostate cancer cells." (PMID 22325146, 2012). "Wnt-3a, Wnt-5a and conditioned medium from prostate cancer cells induced osteoblast differentiation in-vitro and pretreatment of prostate cancer cells with DKK1 diminished osteoblast differentiation." (PMID 22325146, 2012). "Recent studies have shown that Wnt5a protein levels are up-regulated in prostate cancer, but contrasting reports exist on the role of Wnt5a to predict outcome after radical prostatectomy in patients with localized prostate cancer." (PMID 23342259, 2012). "Our results emphasize that Wnt5a can be used as a predictive biomarker, and favoring the view of Wnt5a as a future therapeutic target in prostate cancer patients with tumor cells displaying low expression of Wnt5a." (PMID 23342259, 2012). "Wnt-5a induced the expression of metalloproteinase-1 through the recruitment of JunD and thus contributed to the more aggressiveness of prostate cancer." (PMID 22325146, 2012). "The present tissue microarray study emphasizes the role of Wnt5a protein expression in a different, well-defined, and independent cohort consisting of 312 prostate cancer patients." (PMID 23342259, 2012). "Previous studies report that Wnt5a is upregulated in prostate cancer and suggested that Wnt5a affects migration and invasion of prostate tumor cell." (PMID 22039506, 2011). "This study aimed to evaluate the prognostic value of Wnt5a protein expression in prostate cancer tissue and its potential to predict outcome after radical prostatectomy in patients with localized prostate cancer." (PMID 22039506, 2011). "In a matched pair of prostate cancer and normal cell line, expression of Wnt5A protein was also increased." (PMID 20454608, 2010). "We measured the mRNA levels for WNT5A, previously identified from our oligoarray analysis to be dysregulated in prostate cancer cells." (PMID 20454608, 2010). "We recently showed that WNT5A (one of the 19 members of Wnt family) gene expression is increased (>50 fold) in prostate cancer tissue and cancer cell lines due to hypomethylation." (PMID 20454608, 2010). "Addition of Wnt5A peptide induced calcium waves, lasting upto 100s, in prostate cancer cell line with a 3.1±0.1 (n = 12) fold increase in the intensity of Flou-4 from the base line." (PMID 20454608, 2010). "We show, for the first time, that Wnt5A protein expression is increased in malignant human prostate compared to benign tissue and Wnt/Ca2+ signaling mechanism is activated in prostate cancer cells." (PMID 20454608, 2010). "Increased expressions of Wnt ligands, including Wnt-5a and Wnt-11, are shown in primary prostate cancer tissues and bone-metastasis lesions, and elevated Wnt-11 expression is correlated with PSA levels and implicated in neuroendocrine (NE) transdifferentiation." (PMID 38531859, 2024).